RN7SL231P (RNA, 7SL, cytoplasmic 231, pseudogene)
Gene: Miscellaneous RNA gene on chromosome 19 (14,213,052 to 14,213,323, forward strand). Ensembl gene ENSG00000240803.
Homologues: Orthologues: chimpanzee Metazoa_SRP (99% identical), macaque Metazoa_SRP (81% identical). Paralogues in human: RN7SL316P (97% identical), RN7SL1 (77% identical), RN7SL2 (77% identical), RN7SL3 (76% identical), RN7SL220P (76% identical), RN7SL113P (74% identical), RN7SL126P (74% identical), RN7SL597P (74% identical), RN7SL679P (74% identical), RN7SL732P (74% identical), RN7SL563P (74% identical), RN7SL650P (74% identical), and 703 more.